LINC00664 (long independently transcribed non-coding RNA 664)
Gene: Long non-coding RNA gene on chromosome 19 (21,483,374 to 21,503,238, forward strand). Ensembl gene ENSG00000268658.
Diseases named in the same sentence as LINC00664 in open-access papers:
LINC00664 is named in the same sentence as 6 diseases in open-access papers, as found by Europe PMC text mining. Sharing a sentence is not in itself a finding about the gene and the disease. The quoted sentences say what the papers report.
acute myocardial infarction (1 paper, 2025). Necrosis of the myocardium, as a result of interruption of the blood supply to the area. "On the other hand, a study suggested that LINC00664/hsa-miR-197-3p/JAK2 interaction may be a biomarker for life-threatening myocardial fibrosis after acute myocardial infarction." (PMID 41009512, 2025).
glioma (1 paper, 2023). A benign or malignant brain and spinal cord tumor that arises from glial cells (astrocytes, oligodendrocytes, ependymal cells). "Afterwards, LINC00664 was found to promote cell viability, invasion and migration ability of glioma cells in vitro." (PMID 37403043, 2023). "Firstly, we downregulated the expression level of LINC00664 in U87 and U251 cell lines by small interfering RNA and confirmed that it could promote the proliferation of glioma cells with the CCK8 proliferation assay." (PMID 37403043, 2023).
tumor (2 papers, 2023). "The tumor-associated increase in KLF9 expression was ascribed to KLF9′s stimulation of LINC00664 gene activity, which has been previously shown to promote tumor growth in vitro and in vivo." (PMID 38067370, 2023).
LINC00664 also shares sentences with these, for which no sentence is quoted: cancer (1 paper); Myocardial fibrosis (1); oral squamous cell carcinoma (1).